ENPP4 (ectonucleotide pyrophosphatase/phosphodiesterase 4)
Description:
Hydrolyzes extracellular Ap3A into AMP and ADP, and Ap4A into AMP and ATP. Ap3A and Ap4A are diadenosine polyphosphates thought to induce proliferation of vascular smooth muscle cells. Acts as a procoagulant, mediating platelet aggregation at the site of nascent thrombus via release of ADP from Ap3A and activation of ADP receptors.
Synonyms: AP3Aase; KIAA0879; NPP4
Tractability: Small molecule: a structure with a bound ligand is known. Antibody: UniProt places it where antibodies can reach, with high confidence; its Gene Ontology location is reachable by antibodies, with high confidence; UniProt predicts a signal peptide or a membrane-spanning region. PROTAC: its protein half-life has been measured.
Gene: Protein-coding gene on chromosome 6 (46,129,964 to 46,146,699, forward strand). Ensembl gene ENSG00000001561.
Subcellular location: Cell membrane
Pathways (Reactome):
Immune System: Neutrophil degranulation
Gene Ontology:
Molecular function: bis(5'-adenosyl)-triphosphatase activity; protein binding
Biological process: positive regulation of blood coagulation; purine ribonucleoside catabolic process
Cellular component: extracellular exosome; membrane; ficolin-1-rich granule membrane; plasma membrane
Genetic constraint (gnomAD): Loss-of-function variants: 14 observed, 26.21 expected, observed/expected ratio (o/e) 0.53, 90% interval 0.35 to 0.83. The upper end of that interval is the gene's LOEUF score, 0.83, which puts it in group 3 of 6, group 1 being the genes least tolerant of losing a copy. Missense variants: 403 observed, 479.99 expected, observed/expected ratio (o/e) 0.84, 90% interval 0.77 to 0.91. Synonymous variants: 154 observed, 172.51 expected, observed/expected ratio (o/e) 0.89, 90% interval 0.78 to 1.02.
Homologues: Orthologues: chimpanzee ENPP4 (99% identical), macaque ENPP4 (98% identical), dog ENPP4 (90% identical), rabbit ENPP4 (89% identical), guinea pig ENPP4 (85% identical), pig ENPP4 (84% identical), rat Enpp4 (83% identical), mouse Enpp4 (82% identical), tropical clawed frog enpp4 (58% identical), zebrafish enpp4 (56% identical), Caenorhabditis elegans C01B10.9 (29% identical), Caenorhabditis elegans C27A7.3 (27% identical), and 1 more. Paralogues in human: ENPP5 (45% identical), ENPP1 (36% identical), ENPP3 (34% identical), ENPP2 (32% identical), ENPP6 (30% identical), ENPP7 (28% identical).
Diseases named in the same sentence as ENPP4 in open-access papers:
ENPP4 is named in the same sentence as 5 diseases in open-access papers, as found by Europe PMC text mining. Sharing a sentence is not in itself a finding about the gene and the disease. The quoted sentences say what the papers report.
osteosarcoma (1 paper, 2016). A usually aggressive malignant bone-forming mesenchymal neoplasm, predominantly affecting adolescents and young adults. "Interestingly, ectonucleotide pyrop-hosphatase/phosphodiesterase 4 (ENPP4), involved in hydrolyze phosphodiester bonds and acting as a pro-coagulant and highly expressed in the metastatic osteosarcoma cells, was highly reduced (51.8-fold) in CLL group B." (PMID 27078856, 2016).
cancer (3 papers, 2008 to 2022). A tumor composed of atypical neoplastic, often pleomorphic cells that invade other tissues. "All top five genes, with the possible exception of ENPP4 with no previous report on its role on metastasis, have been reported to be anti-metastatic in different cancer types." (PMID 33562461, 2021).
tumor (2 papers, 2016 to 2019). "Blocking ENPP4 on BAM significantly downregulates the anti-tumor activity of the cell, which demonstrates that ENPP4 has potential tumoricidal activity." (PMID 26823374, 2016). "ENPP4 is a BCG-activated tumoricidal macrophage protein that can indirectly or directly contact receptors such as ATP receptors or insulin receptors on the surface of tumor cells and also destroy the release of tumor cells." (PMID 31885738, 2019). "On the one hand, ENPP4 may catalize the extracellular ATP released from tumor cells and reduce the binding between ATP and ATP receptor, on the other hand, ENPP4 may contact the insulin receptor and inhibit the insulin receptor activity." (PMID 26823374, 2016). "ENPP4 showed a catalytic domain in Asp192, His196, His339 Asp37, Thr73, Asp240, and His241, which suggests that the ENPP4 may affect some receptor such as ATP receptor or insulin receptor on the surface of tumor cells to reduce their proliferation by indirectly or directly contact, receptively." (PMID 26823374, 2016).
ENPP4 also shares sentences with these, for which no sentence is quoted: infection (2 papers); kidney tumours (1).